PAX7 (paired box 7)
Diseases named in the same sentence as PAX7 in open-access papers (continued):
Sharing a sentence is not in itself a finding about the gene and the disease.
cleft palate (1 paper, 2021). Cleft palate is a fissure type embryopathy that affects the soft and hard palate to varying degrees. "The median number of PAX7-positive cells in isolated cleft palate affected tissue was moderate to numerous (++/+++) and the number of PAX7-positive cells (fibroblasts, macrophages, and endothelial cells) in connective tissue ranged from a few (+) to numerous to abundant (+++/++++)." (PMID 34684112, 2021). "Multiple statistically significant moderate correlations (rs = 0.4–0.6) were discovered between the number of PAX7, PAX9, and RYK-positive structures within the epithelium and connective tissue found in the isolated cleft palate affected tissue." (PMID 34684112, 2021). "Our research showed that there are statistically significant differences for the number of PAX7-positive cells in the epithelium and connective tissue between the control group and the unilateral but not bilateral and isolated cleft palate affected tissue." (PMID 34684112, 2021).
craniofacial clefts (1 paper, 2021). "Genome-wide association studies have shown that mutations in the PAX7 gene are associated with the formation of craniofacial clefts." (PMID 34684112, 2021).
dermatomyositis (1 paper, 2023). Dermatomyositis (DM) is a type of idiopathic inflammatory myopathy characterized by evocative skin lesions and symmetrical proximal muscle weakness. "A study comparing the expression of MRFs from muscle biopsies of patients with polymyositis, dermatomyositis, and sIBM showed that there is an increase expression of Pax7, MyoD, Myogenin, and neonatal myosin heavy chain compared with healthy controls." (PMID 36538023, 2023). "Analysis of muscle biopsies from dermatomyositis patients showed that in the advanced stage of perifascicular atrophy there is a perturbation of MRFs expression, characterized by an increase in Pax7 and Myogenin, but not MyoD." (PMID 36538023, 2023).
Esotropia (1 paper, 2021). A form of strabismus with one or both eyes turned inward ('crossed') to a relatively severe degree, usually defined as 10 diopters or more. "Such a mechanism would explain the low expression of MYOD in the lateral rectus muscle of the paralytic esotropia group, while SIX1, PAX7 and MYOG are up-regulated." (PMID 34044792, 2021). "The results of RT-PCR revealed that PAX7, MYOG, PITX1, SIX1 and SIX4 showed higher levels of expression, while that of MYOD a lower level of expression within the paralytic esotropia group as compared with that in the control group (p < 0.05)." (PMID 34044792, 2021).
Facioscapulohumeral dystrophy (1 paper, 2025). Facioscapulohumeral muscular dystrophy (FSHD) is characterized by progressive muscle weakness with focal involvement of the facial, shoulder and limb muscles. "Further analyses including the functional analyses of DUX4, PAX3 and PAX7 in ECs could improve our understanding of a vascular pathogenesis in DUX4-related diseases, particularly in the contexts of cancer and facioscapulohumeral dystrophy." (PMID 40965075, 2025).
heart failure (1 paper, 2022). Inability of the heart to pump blood at an adequate rate to meet tissue metabolic requirements. "Although Pax7 is itself not thought to play a role within cardiac neural crest nor outflow tract development, the presence of edema is suggestive of in utero heart failure." (PMID 35645295, 2022).
hypoxia (1 paper, 2016). A decrease in the amount of oxygen in the body. "Moreover, we found 1.27 ± 0.27 percentage of Pax7+ nuclei (n = 29) on PRE-Hypoxia and 0.75 ± 0.2 (n = 32) on POST-Hypoxia fibers (p = 0.045), a depletion on Pax7+ nuclei number on satellite cells." (PMID 27471475, 2016).
inclusion body myositis (1 paper, 2024). A slowly progressive degenerative inflammatory disorder of skeletal muscles characterized by late onset weakness of specific muscles and distinctive histopathological features. "However, we have also previously reported relatively high numbers of Pax7-positive cells in inclusion body myositis, a chronic condition with limited regenerative capacity." (PMID 39519294, 2024).
iron deficiency (1 paper, 2025). "To determine whether iron deficiency impacts MuSC self‐renewal, we stained for Pax7+ MuSC at 30 dpi." (PMID 41292279, 2025). "Pax7+ MuSC numbers were comparable between IS and ID groups, indicating that mild iron deficiency does not compromise MuSC maintenance after one round of regeneration." (PMID 41292279, 2025). "Treatment with PT2385 significantly increased the number of Pax7+ MuSC and the proportion of Ki67+ proliferating MuSC compared to vehicle‐treated ID controls, indicating that HIF‐2α is a critical mediator of the proliferation block caused by iron deficiency." (PMID 41292279, 2025). "In contrast, ~84% of Pax7+ MuSC in ID muscle were HIF‐2α+, compared to ~22% in IS muscle (white circles), indicating strong stabilization of HIF‐2α in the MuSC population under iron deficiency." (PMID 41292279, 2025).
limb girdle muscular dystrophy type 2A (1 paper, 2021). "The in vivo engraftment potential of GSH-generated PAX7+ myogenic progenitors was also validated in immunodeficient mouse models of DMD and limb girdle muscular dystrophy type 2A." (PMID 33275879, 2021).
myopia (1 paper, 2022). "On the one hand, the results of Metascape revealed a potential role of TF in the development of myopia with the enrichment of Smad6, NrOb2, Gtf2i, Tfap2a, Pax7, Pax6, Sox9 and Smad3." (PMID 34841657, 2022).
Neurodevelopmental delay (1 paper, 2023). "Another differential splicing of the Pax7 gene appears crucial for function: indeed, a splicing mutant resulting in loss of the OAR-containing isoform of human PAX7 is associated with a global neurodevelopmental delay." (PMID 37326021, 2023).
ptosis (1 paper, 2019). The drooping of the upper eyelid. "The presence of the severe congenital ptosis in the PAX7null patient indicates that the role of PAX7 in head muscles needs further investigation." (PMID 31852888, 2019).
renal carcinoma (1 paper, 2014). A carcinoma arising from the epithelium of the renal parenchyma or the renal pelvis. "Previous studies have illustrated that Pax3 and Pax7 are associated with cell survival in numerous cancer cell lines and silencing of pax2 promotes renal carcinoma apoptosis." (PMID 25197636, 2014).
soft tissue tumors (1 paper, 2023). "In addition to the traditional immunohistochemical markers that are applied for diagnosing SS, we also explored the diagnostic value of a panel of markers that have recently been used in other soft tissue tumors, such as SOX-2, PAX-7, NKX3.1 and INI-16,16–19." (PMID 37193761, 2023).
spina bifida (1 paper, 2022). A congenital neural tube defect in which vertebrae are not fully formed. "However, the removal of one Pax7 allele was sufficient to significantly increase the frequency of neural tube defects (from 66% Pax3neo/∆5/Pax7+/+ having spina bifida and/or exencephaly to 95% (n = 47/49) of Pax3neo/∆5/Pax7Δ2/+ having spina bifida and/or exencephaly)." (PMID 35645295, 2022).
Stress urinary incontinence (1 paper, 2021). Involuntary urine leakage synchronous with exertion, or actions such as sneezing, or coughing. "ADSCs-extracellular vesicles treatment upregulated expression of Elastin, Collagen I, and Collagen III in stress urinary incontinence primary fibroblasts and expression of Pax7 and MyoD in stress urinary incontinence primary satellite cells." (PMID 34484115, 2021). "Stress urinary incontinence primary fibroblasts or satellite cells were treated with ADSCs-extracellular vesicles to detect the expression of Elastin, Collagen I, and Collagen III in fibroblasts and Pax7 and MyoD in satellite cells." (PMID 34484115, 2021).
thymoma (1 paper, 2024). A neoplasm arising from the epithelial cells of the thymus. "Types A, AB, and B2 thymomas share many of these genes, with additional occurrences of PAX7 and CSF1R in Type A thymoma and ZMYM3 in Type AB thymoma." (PMID 38338833, 2024).
ZIKV infection (1 paper, 2021). "The induction of PAX-7 expression by ZIKV infection shows that it promotes the activation of satellite cells." (PMID 34468171, 2021). "ZIKV infection promoted a significant increase in the mRNA expression of PAX-7, which is responsible for preserving undifferentiated muscle satellite cells but is also an early myogenic activation factor after injury." (PMID 34468171, 2021).
tumor (63 papers, 2003 to 2026). "Age, IRS group, tumor size, site and invasiveness, nodal status and fusion type (PAX7:: vs. PAX3::FOXO1) were significantly associated with OS." (PMID 39781573, 2025). "We previously demonstrated weak Pax3::Foxo1 RNA expression in Pax7 CreER tumours with the Pax3::Foxo1 knock‐in allele compared to much higher Pax3::Foxo1 expression in tumours forming after Pax3::Foxo1 was knocked into the other lineages." (PMID 39812007, 2025). "In concert with these findings, the DM/DE genes between Myf5 and Pax7 lineage‐related tumours are associated with muscle development‐related gene subsets." (PMID 39812007, 2025). "Our finding of a striking difference in DNA methylation patterns between mouse RMS tumours in which driver mutations were directed to the Myf5 or Pax7 lineage is consistent with the dynamic events that occur during myogenic development." (PMID 39812007, 2025). "Our analysis demonstrated that the Pax7 lineage was tightly associated with mouse tumours in the MR cluster (9/20, 45%) compared with that in the ML cluster (0/11, 0%) (p = 0.012)." (PMID 39812007, 2025). "Deleting Pax7 in ASPcKO mice rescued the decreased tumor-free survival and increased tumor mass associated with Pten loss in the AS mice." (PMID 34535684, 2021). "In contrast to modulating the PI3K/AKT/mTOR pathway, we reveal PTEN loss drives a transcriptional axis centered on PAX7 necessary for FN-RMS tumor identity." (PMID 34535684, 2021). "Our analyses confirmed that the delayed muscle regeneration observed in muscles form tumor-bearing mice was associated with a persistent local inflammation and Pax7 overexpression." (PMID 27034684, 2016). "Based on their genotypes, we identified n = 23 tumours corresponding to the ML cluster (Pax3::Foxo1 in Myf5, Myf6, or Pax3 lineage) and n = 33 tumours corresponding to the MR cluster (other mutations in any lineage or Pax3::Foxo1 in Pax7 lineage)." (PMID 39812007, 2025). "This work intertwines the interplay between context-dependent tumor suppressor loss and transcriptional activation can engage a synthetic essential pairing; here, the combination of PTEN loss and PAX7 activation not only maintains tumor growth and survival but maintains tumor identity." (PMID 34535684, 2021). "Higher expression of ICAMs and VLA integrins in RH30 PAX7+ cells may be responsible for tumor progression in vivo, as their levels were previously associated with tumor progression." (PMID 34440639, 2021). "It has also been shown that Pten loss drives Pax7 mRNA increases in human neural stem cells further highlighting how transcriptional regulation by PTEN may be a critical mediator of its tumor suppressor functions." (PMID 34535684, 2021). "After analysing the RNA‐seq data from the TCGA database consistently, we discovered that PAX7 exhibited varied expression levels in seven tumours when compared to normal samples." (PMID 40370330, 2025). "In particular, we compared differential expression between four Myf5 lineage tumours and 10 Pax7 lineage tumours using available gene expression data." (PMID 39812007, 2025). "Our research group revealed the differential expression of PAX7 in seven tumours through analysis of TCGA database RNA‐seq data." (PMID 40370330, 2025). "Our previous studies utilizing the NSG mouse tumor model demonstrated a significant increase in Pax7 expression and a notable decrease in Myod1 in the GA muscles of tumor-bearing, vehicle-treated mice compared to tumor-free controls." (PMID 39996717, 2025). "This latter finding can be explained by the very low expression of Pax3::Foxo1 in these Pax7 lineage tumours, resulting in an inadequate amount of Pax3::Foxo1 to modulate the epigenetic landscape in this setting." (PMID 39812007, 2025). "Of note, most of these DM/DE genes were hypomethylated and overexpressed in the MR1/Myf5 compared to the MR2/Pax7 tumours." (PMID 39812007, 2025).
tumor (continued). "The increased Pax7 levels in the myotubes exposed to CM-C26 for 48 h are consistent with a previous observation showing that Pax7 is overexpressed in the skeletal muscle of mice implanted with a C26 tumor." (PMID 38732549, 2024). "The tumor-free WFA 4 mg/kg group displayed the highest proportion of Pax7+ cells, suggesting that WFA is a potent activator of satellite cells." (PMID 33718372, 2021). "Here, the authors use a Hedgehog-driven FN-RMS mouse model to show that PTEN loss drives the expression of core transcription factor PAX7 and its transcriptional axis, which determines FN-RMS tumour identity." (PMID 34535684, 2021). "There was also a significant increase in the amount of Pax7+ cells in the tumor-bearing vehicle-treated group (0.34 ± 0.01) compared to the tumor-free vehicle-treated group (p < 0.0001)." (PMID 33718372, 2021). "In both SJRHB015721_X1 and SJRHB012405_X1 PDXs, PAX7 knockdown with shPAX7 resulted in decreased tumor volume; however, tumor mass only decreased in SJRHB015721_X1." (PMID 34535684, 2021). "The tumor-free and tumor-bearing WFA-treated groups displayed significant increases in Pax7 compared to the tumor-free vehicle-treated group and a significant increase in Myod1 compared to both vehicle-treated groups." (PMID 33718372, 2021). "The original report comparing CIC-DUX4 and EWSR1-NFATc2 positive tumors identified key molecular markers differentiating the two diseases; presenting PAX7 as a highly specific marker for EWSR1-NFATc2 positive tumor diagnosis." (PMID 34021224, 2021). "Similar to the IHC data, the tumor-bearing vehicle-treated group displayed a significant increase in relative transcript levels of Pax7 and a significant decrease in Myod1 compared to the tumor-free vehicle-treated group." (PMID 33718372, 2021). "Consistent with published reports, the majority of the satellite cells in the tumor-free vehicle-treated group were Pax7+/MyoD– (96.29 ± 0.69%) and a small population was found to be Pax7+/MyoD+ (3.71 ± 0.69%)." (PMID 33718372, 2021). "This synthetic essential relationship between Pten and Pax7 highlights the complex interplay between genetic alterations and transcriptional states that not only define tumorigenicity but even tumor origin and evolution." (PMID 34535684, 2021). "Focusing on this latter, experimental studies performed in mice hosting the C26 tumor have shown in the muscle increased expression of Pax7, a marker of satellite cell activation, and reduced levels of myogenin, an indicator of ongoing differentiation." (PMID 30833900, 2019). "Using a median cutpoint based on the gene expression values of Pax7 and Sox2, we plotted PAs according to the high or low expression of these genes relative to the rate of secondary tumor sphere formation." (PMID 27894339, 2016). "To further investigate the procachectic role of Pax7 in skeletal muscle tissue in tumor-bearing mice, we characterized the cellular response to muscle damage occurring in muscles obtained from cachectic mice after acute damage." (PMID 27034684, 2016). "To verify if physical activity affects Pax7 expression, we hosted control and C26-bearing mice in wheel-equipped cages and we found that voluntary wheel running downregulated Pax7 expression in muscles from tumor-bearing mice." (PMID 27034684, 2016). "We found that majority of genes (19/23) whose transcripts were co-upregulated by PAX7 overexpression and PTEN-knockout are associated with tumour-promoting or increased cellular mobility." (PMID 26632666, 2015). "Future studies will address the salivary cell subtypes belonging to the Pax7, Myf5, and Myf6 lineages, timing of tumor initiation, and the potential stem-cell like plasticity of this ontogeny." (PMID 25883905, 2015). "For U23674 tumor cells of the Myf6Cre myoblast lineage, a decrease in both Pax7 and Pax3:Foxo1 mRNA levels upon treatment with all of the drugs was observed, but the effect was more pronounced for HDAC inhibitors." (PMID 25030697, 2014).